RN7SL570P (RNA, 7SL, cytoplasmic 570, pseudogene)
Gene: Miscellaneous RNA gene on chromosome 9 (69,884,363 to 69,884,654, reverse strand). Ensembl gene ENSG00000241174.
Homologues: Orthologues: chimpanzee Metazoa_SRP (99% identical), macaque Metazoa_SRP (91% identical). Paralogues in human: RN7SL2 (74% identical), RN7SL1 (74% identical), RN7SL3 (74% identical), RN7SL302P (73% identical), RN7SL481P (73% identical), RN7SL126P (73% identical), RN7SL665P (73% identical), RN7SL242P (73% identical), RN7SL49P (73% identical), RN7SL218P (72% identical), RN7SL228P (72% identical), RN7SL408P (72% identical), and 704 more.